FOXO1 (forkhead box O1)
Diseases named in the same sentence as FOXO1 in open-access papers (continued):
Sharing a sentence is not in itself a finding about the gene and the disease.
Insulin resistance (continued). "By enhancing the phosphorylation of IRS on Ser307 and destroying its downstream Foxo1 phosphorylation aggravates insulin resistance, which contribute to inflammation and insulin resistance." (PMID 29207597, 2017). "Palmitate induced insulin resistance as indicated by impaired insulin-induced phosphorylation of insulin receptor, Akt, Gsk3β and FoxO1." (PMID 28933767, 2017). "Our data indicate that the transcriptional factor Foxo-1 is essential in mediating the effect of exendin-4 on adiponectin, suggesting Foxo-1 as a potential target for treating diet-induced insulin resistance and diabetes." (PMID 28122026, 2017). "The dysregulation of FOXO1 that accompanies insulin resistance is reflected in our observation that MARCH1 expression is increased in WAT from obese adolescent humans." (PMID 27577745, 2016). "Insulin resistance also induces the expression of key inflammatory cytokine genes such as interleukin 1-beta in macrophages due to the interaction of NF-κB and FoxO1, a key transcription factor mediating insulin action." (PMID 27189661, 2016). "For this purpose we generated a GFP-labelled biosensor based on FoxO1, a transcription factor that resides in the cytoplasm in insulin-sensitive cells and translocates into the nucleus under conditions of insulin resistance." (PMID 26899548, 2016). "This emphasizes the role of FOXO1 transcription factor as a central mediator of inflammation in the perspective of insulin resistance and obesity." (PMID 26956801, 2016). "Nevertheless, this state of fructose-induced insulin resistance is atypical, as FoxO1 phosphorylation is increased and therefore the expression of gluconeogenic genes is not induced." (PMID 27194405, 2016). "Since insulin is involved in FOXO1 repression, FOXO1 is stimulated in insulin resistance condition where diminution of insulin signalling pathway prevails, leading to accelerated inflammatory response." (PMID 26956801, 2016). "FOXO1 emerges as a potential regulator of different kinds of cell death during insulin resistance and diabetes." (PMID 26956801, 2016). "FOXO1 can modulate glucose metabolism in adult cardiomyocytes in insulin resistance and diabetic conditions by inhibiting glucose oxidation preceded by PDK4 activation, subsequently altering the substrate preference for fatty acid and lactate." (PMID 26956801, 2016). "Significantly improved insulin resistance by restoring hepatic FOXO1 nuclear translocation and upregulating gene expression of Akt2, Irs1, Irs2, Pi3kca, Pi3kcg and Pdk1." (PMID 25621503, 2015). "This highlights the role of FOXO1 as a key molecular proinflammatory transcription factor in the context of obesity and insulin resistance." (PMID 24864265, 2014). "Among them, miR-182 related to the insulin resistance by modulating FOXO1 and PI3K/AKT cascade and had the greatest copy number in the whole blood." (PMID 25530976, 2014). "Abnormalities in the signaling pathway, including IRS1, FOXO1 and GSK3β, marked the main characteristics of insulin resistance in Huh7-Pre-miR190b-6 cells." (PMID 24586785, 2014). "The acute worsening of insulin resistance, despite enhanced Akt phosphorylation and Akt-FoxO1 signaling, highlights that acute regulation of hepatic glucose production by insulin is unlikely to be mediated by transcriptional changes in gluconeogenic enzymes." (PMID 24150286, 2013). "Future studies will clarify the physiological relevance between FoxO1 and compensatory β cell hyperplasia against insulin resistance." (PMID 22384192, 2012). "Under conditions of insulin resistance, there are insufficient mitochondria and abnormal mitochondrial morphology, which is reversed when FOXO1 is deleted." (PMID 22454632, 2012). "In contexts of insulin resistance, reduction of hepatic FoxO1 activity substantially ameliorates dysregulation of glucose metabolism in mice." (PMID 20975207, 2010).
Insulin resistance (continued). "Recent findings suggest that FoxO1 integrates insulin signalling with hepatic mitochondrial function and inhibition of Foxo1 can improve hepatic metabolism during insulin resistance and the metabolic syndrome." (PMID 20480025, 2010). "This resulted in the insulin resistance marked by the down-regulation of insulin receptor signalling (Irs1, Foxo1, and Foxo3a), and down-regulation of Glut4." (PMID 19344534, 2009). "In addition, miR-27a-3p has been shown to enhance muscle glycogen storage and alleviate insulin resistance by modulating FOXO1 signaling and downregulating gluconeogenic enzymes." (PMID 41282288, 2025). "In obese PCOS, the altered inflammatory milieu—driven by TNF-α, IL-6, and resistin—can induce the release of EVs enriched with pro-inflammatory microRNAs that disrupt IRS phosphorylation, impede GLUT4 translocation, and modify FOXO1-mediated transcription, thereby exacerbating insulin resistance." (PMID 41010046, 2025). "The upregulation of lncMEG3 exacerbates hepatic insulin resistance by increasing FOXO1 expression." (PMID 40242439, 2025). "Furthermore, in another study, the expression levels of p-FOXO1/FOXO1 in Lycium ruthenicum anthocyanin-treated insulin resistance (IR) Hep-G2 cells were significantly reduced as compared to the normal cells." (PMID 40218884, 2025). "ECD also resolved hepatic insulin resistance by activating the IRS1-Akt-FoxO1 pathway." (PMID 41304952, 2025). "Consequently, oleate shifted the transcriptional balance from Wnt/β-catenin signaling to FoxO1-mediated transcription, impairing the compensatory response of beta cells to insulin resistance." (PMID 39940428, 2025). "It phosphorylates pro-apoptotic effectors (BAD, FOXO1) to enhance thyrocyte and orbital fibroblast survival, while mTORC1 hyperactivation accelerates metabolism, contributing to hypermetabolic phenotypes and insulin resistance." (PMID 41155084, 2025). "The PI3K/AKT pathway can be activated to mediate SREBP regulation of fatty acid synthesis and FOXO1 signal pathway for fatty triglyceride lipase (ATGL) regulation of lipolysis, increasing glucose utilization and body fat deposition and reducing insulin resistance caused by obesity." (PMID 38947127, 2024). "The combined treatment of catechin epigallocatechin gallate (EGCG) and quercetin prevented insulin resistance by increasing the expression of miR-27a-3p and miR-96-5p, which directly target Forkhead Box O1 (FOXO1), reducing the production of glucose and the transcription of gluconeogenic enzymes." (PMID 38201989, 2024). "Furthermore, we have previously reported that laccaic acid, known for its anti-inflammatory properties, reduces gluconeogenesis and alleviates insulin resistance by restoring the high-fat diet induced epigenetic alterations around the FOXO1 promoter." (PMID 38745315, 2024). "Notably, in the context of increased global levels of H3K36me2 under diet-induced insulin resistance, these studies have underscored the crucial involvement of H3K36me2 in enhancing the FOXO1 expression." (PMID 38745315, 2024). "Therefore, the myocardin-mediated increase in FoxO1 expression is a result of myocardin-induced insulin resistance." (PMID 38505620, 2024). "Interestingly, our ChIP experiments revealed that palmitate-induced insulin resistance increased the enrichment of H3K36me2 around FOXO1 promoter along with reduced expression of Kdm2a, which was restored by miR-721 inhibition." (PMID 38745315, 2024). "Consequently, exogenous NTs ameliorate insulin resistance in HepG2 cells by modulating the IRS-1/AKT/FOXO1 pathways and regulate glucose consumption, glycogen content, insulin signaling pathways, AMPK activity, oxidative stress, and inflammatory status." (PMID 38931156, 2024). "Insulin resistance can develop in endothelial cells, and it may be hypothesized that Dex-mediated upregulation of Foxo1 expression in LSEC over time can lead to insulin resistance in these cells." (PMID 39439887, 2024).
Insulin resistance (continued). "In addition, a study showed that HFD-induced mice and PA-induced HepG2 cells treated with quercetin saw a enhancement alleviation of insulin resistance via the IRS-1/AKT/FoxO1 pathway, and stimulated expressions of p-IRS1, p-AKT and GLUT4 in liver." (PMID 38799166, 2024). "Foxo1 was mainly involved in insulin resistance and lipid metabolism." (PMID 37033250, 2023). "This overexpression increases the uptake of glucose by muscle tissue and activated the PI3K/Akt-1 pathway by upregulating Akt-1 expression, which in turn leads to a decline in the expression levels of Foxo-1 and Pdk-4 to counteract the excess of glucose and inhibit the insulin resistance." (PMID 37584728, 2023). "Moreover, studies indicates that as insulin resistance and OS progresses, FoxO1 acts to combat these conditions but over time its protein levels decline causing β-cell dedifferentiation and marking a molecular switch to T2D pathology." (PMID 37941908, 2023). "Moreover, GCs stimulate serum- and GC-inducible kinase 1 (SGK1), which raises the phosphorylation of the forkhead box protein O1 (FOXO1) and lowers the phosphorylation of protein kinase B in adipocytes, resulting in insulin resistance." (PMID 37842314, 2023). "Recent work shows that lack of the vitamin D receptor in skeletal muscle increases FoxO1 activity and causes insulin resistance and glucose intolerance." (PMID 37941908, 2023). "Macrophage FoxO1 activity, which remains at baseline in naive macrophages, is markedly upregulated in hepatic and adipose tissue macrophages in response to metabolic stress such as overnutrition and insulin resistance." (PMID 35700043, 2022). "miR-223 regulated insulin resistance by targeting FOXO1 in a study using HepG2 cells." (PMID 36297381, 2022). "In line with this, knockdown of FOXO1 in mouse adipose tissue improved insulin resistance." (PMID 35739982, 2022). "Moreover, insulin resistance dampens the inhibitory effect of insulin on FOXO1 and leads to persistent nuclear FOXO1 activity." (PMID 35868560, 2022). "FoxO1 knockout in the mouse livers could afford an improvement in glucose homeostasis and subsequently reduce insulin resistance." (PMID 35432202, 2022). "However, more research should be carried out to investigate the role of miR-1224-5p and FOXO1 in the insulin resistance in PCOS." (PMID 34637688, 2021). "The differences might be due to the fact that FOXO1 is involved in insulin resistance and cytokine‐mediated β‐cell failure in type 2 diabetes patients." (PMID 33609082, 2021). "Increased hepatic miR-486 expression may also reduce Foxo1, resulting in reduced insulin resistance that may then affect fertility." (PMID 36303988, 2021). "However, overactive FoxO1 induces gluconeogenesis in such an unregulated manner under insulin resistance conditions that it contributes to hyperglycemia." (PMID 33804729, 2021). "The nuclear exclusion of FoxO1 is necessary for β-cell proliferation in the insulin resistance state), but under these conditions, a decrease in Akt activity alleviates the inhibition of FoxO1, which translocates to the nucleus and represses its target genes like PDX-1." (PMID 34638652, 2021). "The concomitant invalidation of FOXO1 was sufficient to suppress this insulin resistance." (PMID 33435513, 2021). "The importance of FOXO1 in hepatic insulin resistance was demonstrated using transgenic animals." (PMID 33435513, 2021). "The inhibition of miR-192-5p promotes hepatic steatosis and insulin resistance by targeting FOXO1." (PMID 33708127, 2021). "They used miRNA‐223 KO mice and found that these mice exhibit increased expression of both Sox6 and Foxo1 (forkhead box O1) genes, and impaired glucose tolerance and insulin resistance as a result of the suppression of β‐cells proliferation and insulin secretion." (PMID 33230925, 2020). "Based on previous study, Foxo1 could involve in insulin resistance and dysregulated glucose metabolism in the liver." (PMID 32286278, 2020).
Insulin resistance (continued). "Based on in vivo and in vitro results, we hypothesized that the SIRT1/FOXO1 pathway plays an important role in improving insulin resistance under MNAM treatment." (PMID 32280711, 2020). "Moreover, FOXO1 knockout ameliorated cardiomyocyte dysfunction and insulin resistance in diabetic mice." (PMID 33028948, 2020). "Subsequent studies employing insulin stimulation prior to euthanasia also revealed that 17α-E2 robustly increased liver AKT and FOXO1 phosphorylation in male WT mice, indicating a reversal of obesity-related hepatic insulin resistance and increased control of gluconeogenesis." (PMID 33289482, 2020). "Furthermore, ROS reduces insulin signalling and induces subsequent insulin resistance, yielding elevated FoxO1 activation." (PMID 33108705, 2020). "In this study, Notch1 was up-regulated while FoxO pathway was over-represented, Notch1 could up-regulate FoXO1 which aggravated insulin resistance of NAFLD." (PMID 31805951, 2019). "Our study also suggests that HDAC4‐mediated FoxO1 deacetylation could represent a novel target for pharmacotherapy, not only of decreasing glucose‐sensitive insulin secretion but also for insulin resistance." (PMID 30968599, 2019). "FOXO1 has been shown to be involved in muscle atrophy and insulin resistance." (PMID 31492105, 2019). "Our previous study showed that piceatannol could inhibit TNF-α-mediated inflammation and insulin resistance in 3T3-L1 adipocytes through Akt-dependent forkhead box O1 (FoxO1) signaling pathway." (PMID 31277394, 2019). "In addition, the insulin signaling pathway (IRS-1/AKT/FOXO1) was activated, further demonstrating that Nifu mitigates PA-induced insulin resistance by activating insulin signaling." (PMID 35540668, 2019). "Besides reducing acetylation of PGC-1α, we also found that PGRN-Sirt1 signaling regulates the activity of transcription factor FoxO1, which plays an important role in aging, cell metabolism, insulin resistance, and oxidative stress resistance." (PMID 31285425, 2019). "Consequently, under insulin resistance conditions, FoxO1 phosphorylation is blunted, and the transcriptional activation of gluconeogenic genes is abnormally sustained, which confers increased susceptibilty to type 2 diabetes (T2D) mellitus." (PMID 29052178, 2018). "Furthermore, placental FOXO1 mRNA expression was significantly correlated with the HOMA-IR (Homeostatic Model Assessment of Insulin Resistance) in the GDM group." (PMID 30558244, 2018). "Evidence constantly emerges that transcription factors, including FOXO1, co-factors and chromatin modifications, like post-translational histone modifications, interact on various levels of gene expression and through this, contribute to insulin resistance." (PMID 30558244, 2018). "Therefore, it can be concluded that insulin resistance can be improved by targeting the expression of FOXO1 in the adipose tissue by specific agents." (PMID 31565649, 2018). "However, insulin resistance promotes FoxO1 activation by reducing insulin signaling, resulting in dephosphorylation of the FoxO1 allowing its entry into the nucleus." (PMID 30424007, 2018). "Additionally, in vitro conditions that mimic hyperglycemia and insulin resistance increase FoxO1 protein and activity in EC." (PMID 30511639, 2018). "Consequently, they enhanced hepatic insulin resistance via increased expression of forkhead box O1 (FoxO1), a critical regulator of hepatic glucose and lipid metabolism via its ability to regulate the expression of G6pc and Pepck in gluconeogenesis." (PMID 29050364, 2017). "FOXO1 upregulation in insulin resistance state may lead to impairment of cardiac contractility by increasing β-myosin heavy chain gene expression in cardiac cells." (PMID 26956801, 2016).
Insulin resistance (continued). "Decreasing Akt activity by incubating MIN6 cells with the pharmacological inhibitor Akti-1/2 (10 μM) and thus mimicking insulin resistance led to an increase in the nuclear localization of FoxO1(H215R)GFP (green signal), while the reference Tomato (red signal) remains cytosolic." (PMID 26899548, 2016). "Additionally, FOXO1 is markedly activated during fasting, a condition used for the study of glucose intolerance and insulin resistance." (PMID 26219821, 2015). "FOXO1 activity may explain the abnormal production of proinflammatory cytokine IL-1β and in conditions where there is insulin resistance." (PMID 24864265, 2014). "FOXO1 is found to be a central player in -cell compensation of insulin resistance." (PMID 24244124, 2013). "We reasoned that identification of FoxO1 target genes in β-cells could reveal mechanisms linking β-cell dysfunction to insulin resistance." (PMID 23705021, 2013). "In the state of insulin resistance, FoxO1 should be dephosphorylated and activated in β cells." (PMID 22384192, 2012). "Thus, a pathway exists whereby insulin resistance leads to elevated FOXO1 activation, upregulation of genes that promote glucose production, and greater serum glucose levels." (PMID 22454632, 2012). "Thus, when FOXO1 activity is elevated by insulin resistance, greater expression of heme oxygenase-1 ensues." (PMID 22454632, 2012). "Indeed, circHIPK3 contributes to hyperglycemia and insulin resistance by disturbing the miR-192-5p/FOXO1 axis homeostasis and is upregulated in type II diabetes patients, and it was found upregulated in acute pancreatitis, an important risk factor for the pancreatic cancer development." (PMID 40061896, 2025). "Thus, targeting FoxO1 and developing strategies for tissue-specific delivery of FoxO1 therapeutics can serve as an effective approach for treating type 2 diabetes mellitus and improving insulin resistance." (PMID 39944202, 2025). "The loss of FOXO1 and PDX1 transcription factor signaling in pancreatic β-cells, which results in the loss of insulin production prevalent in pathological conditions such as insulin resistance and T2DM, has been broadly demonstrated and identified as a key clinical target 1,40,41." (PMID 40585255, 2025). "Therefore, further targeted studies are warranted to clarify whether SPX acts via GALR2 to influence insulin resistance and hepatic metabolism, and to explore the involvement of the FOXO1/PGC-1α pathway in these processes." (PMID 40841811, 2025). "Fisetin supplementation could ameliorate hyperlipidemia and insulin resistance through regulating the IRS1Tyr608/AKT/GSK3β/FoxO1 signaling pathway, the expression of phosphorylated IRS1Tyr608, AKT, FoxO1 and GSK3β was markedly decreased by the intervention of fisetin in the kidneys of HFD-fed mice." (PMID 38799166, 2024). "Moreover, SH and UA treatment upregulated the expression of IRS-1, AKT, and GLUT4, which are suppressed in insulin resistance, to a similar degree to metformin, and suppressed the expression of FoxO1, PEPCK involved in gluconeogenesis, and GSK-3β involved in glycogen metabolism." (PMID 37754257, 2023). "Regarding insulin resistance, PC-derived exosomes were found to readily enter C2C12 myotubes, causing lipidosis and the inhibition of glucose uptake by impairing glucose transporter type 4 (GLUT4) trafficking and preserving forkhead box protein O1 (FOXO1) nuclear exclusion." (PMID 37373351, 2023). "In addition, we have provided evidence that FoxO1 mediates the beneficial effect of estrogen on glucose dysregulation and heart failure under insulin resistance; these results indicate that FoxO1 signaling contributes to the sex dimorphism observed in heart diseases and diabetes." (PMID 37960324, 2023).